BLCAP (BLCAP apoptosis inducing factor)
Diseases named in the same sentence as BLCAP in open-access papers (continued):
Sharing a sentence is not in itself a finding about the gene and the disease.
medullary thyroid carcinoma (1 paper, 2019). "In addition, it has been reported that BLCAP can be regulated by miR-9-3p to promote cell growth and inhibit apoptosis in medullary thyroid carcinoma, and there was only one potential complementary site for miR-339-5p in the 3′UTR of BLCAP mRNA." (PMID 30683807, 2019).
metastatic melanoma (1 paper, 2018). A melanoma that has spread from its primary site to another anatomic site. "In addition, the overall frequency of the BLCAP mRNA, a known substrate for ADAR1 A-to-I editing, was found to be 11% in normal melanocytes but only 5.5% in metastatic melanoma cells." (PMID 29386624, 2018).
pregnancies (1 paper, 2024). "Another tumor suppressor gene, bladder cancer-associated protein (BLCAP), has been found to be significantly expressed in the placenta of women with perinatal ectopic pregnancies." (PMID 38978060, 2024).
sarcoma (1 paper, 2013). A usually aggressive malignant neoplasm of the soft tissue or bone. "However, the DNA methylation status of the BLCAP promoter was not significantly different in our sarcoma collection, and BLCAP had homogeneous high expression levels." (PMID 24345474, 2013).
urothelial cancer of the bladder (1 paper, 2021). "BLCAP exhibits a tumor suppressor function in various tumors, including urothelial cancer of the bladder and can reduce cell growth by stimulating apoptosis." (PMID 34943506, 2021). "The increase in BLCAP by B. pullicaecorum administration and butyrate treatment may reflect cell cycle arrest, FasL expression, and growth inhibition in NaB-treated bladder urothelial cancer cells." (PMID 34943506, 2021).
urothelial carcinoma (1 paper, 2012). A malignant neoplasm derived from the transitional epithelium of the urinary tract (urinary bladder, ureter, urethra, or renal pelvis). "One of the biomarkers we discovered, Bladder Cancer Associated Protein (BLCAP), was originally identified by our laboratory in a small study comprising 30 urothelial carcinomas (UCs) where we showed that loss of BLCAP mRNA expression correlates with the invasive potential of UCs." (PMID 23049907, 2012). "We showed previously that in urothelial carcinomas, in most cases, BLCAP protein expression was lost with tumor progression." (PMID 23049907, 2012).
tumor (23 papers, 2006 to 2025). "Hyper RNA editing of BLCAP is positively associated with tumor size and tumor numbers, suggesting that editing of BLCAP contributes to hepatocarcinogenesis." (PMID 30585209, 2018). "Bladder cancer-associated protein (BLCAP) gene is a highly conserved gene with tumor-suppressor function in different carcinomas." (PMID 28455960, 2017). "Although BLCAP exhibits tumor-suppressive effects in various cancers, edited BLCAP mainly exerts pro-cancer effects." (PMID 37328893, 2023). "As an apoptosis-inducing factor, BLCAP can initiate apoptosis in many tumors and is considered a tumor suppressor gene." (PMID 37055532, 2023). "Analysis of expression of imprinted genes in the pancancer data confirmed the association of increased expression of two genes, BLCAP and HM13, at 20q11-q13.32 with tumor cell resistance to multiple agents." (PMID 36461044, 2022). "BLCAP inhibits the cell cycle, induces apoptosis as an apoptotic inducer, and acts as a tumour suppressor gene." (PMID 35610231, 2022). "Western blot analysis showed that tumor cells overexpressing PRADX had reduced levels of BLCAP and increased nuclear levels of phosphor(p)-STAT3." (PMID 35574370, 2022). "BLCAP, a highly conserved gene with tumor-suppressor function in different carcinomas, was previously identified as an edited gene in the brain and fat tissue of pig, and the same Y/C editing site is mapped in the key YXXQ motif in human." (PMID 30918658, 2019). "Specimens with tumor cells displaying marked nuclear immunoreactivity for BLCAP were also observed in 19% (19 out of 101; with 1% or more cells having nuclear staining) of the tumor specimens examined (red arrow)." (PMID 23049907, 2012). "We obtained interpretable staining results for BLCAP in a total of 101 tumor samples; the reason for failure was insufficient tumor cells available for scoring." (PMID 23049907, 2012). "In spite of this marked intertumoral heterogeneity, only two cases - DCTB sample pairs 22 and 93, displayed decreased expression levels of BLCAP in tumour tissue as compared to matched normal tissue." (PMID 23049907, 2012). "In order to objectively evaluate this differential BLCAP expression in tumor cells we performed quantitative IHC analysis of BLCAP expression in breast tissues." (PMID 23049907, 2012). "This direction of association could be due to potential therapeutic vulnerability of tumor cells with fewer copies of the BLCAP gene and lower BLCAP expression." (PMID 36461044, 2022). "Therefore, potential effects of nuclear or cytoplasmic localization of BLCAP on tumor response to treatment warrant further investigation." (PMID 36461044, 2022). "In the future, we will investigate the relation of BLCAP tumor methylation with survival outcomes." (PMID 35063012, 2022). "Our research delineate a new mechanism of BLCAP function as a tumor suppressor, and provide additional evidence that abnormal A-to-I RNA editing events alter the function of BLCAP by editing the critical sites and play a potential role in progression of cervical carcinogenesis." (PMID 28455960, 2017). "Other researchers reported that overexpression of BLCAP induced cell growth inhibition and apoptosis, suggested that BLCAP may function as a potential tumor suppressor in carcinogenesis through regulating cell proliferation and survival." (PMID 28455960, 2017). "But it also raises one vital question, since at first sight these observations are incongruent with the idea that BLCAP may have a tumor-suppressor function." (PMID 23049907, 2012). "In general, tumor samples showed increased expression of BLCAP as compared to normal samples." (PMID 23049907, 2012). "In addition, over-expression of BLCAP in human TC-135 Ewing’s sarcoma cells and HeLa cervical cancer cells resulted in cell growth inhibition and induced apoptosis, indicating a role for this protein in the regulation of tumor cell proliferation and survival." (PMID 23049907, 2012).
tumor (continued). "Results confirmed that BLCAP, EML1, FOSL2, ADNP and FRMD3 were deregulated in the same way among the xenografts, FFPE and OCT tumour samples." (PMID 30592148, 2019). "We performed RNA editing analysis of the Gabra-3 I/M site (edited by both ADAR1 and ADAR2), the BLCAP Y/C, Q/R sites (edited by both ADAR enzymes) and the K/R site (edited mainly by ADAR2) in the tumor tissues of Case 4 and controls." (PMID 23697632, 2013). "In five cases we found similar expression levels of BLCAP in normal and tumour samples (DCTB pairs 19, 42, 45, 87 and 95), whereas in the 55 remaining cases (88%) we observed increased BLCAP expression in tumour samples relative to the matched normal tissue." (PMID 23049907, 2012). "In addition, other genes have been involved in cancer processes, such as interference with innate immune system (SH2D3C), apoptosis (BLCAP), crossing-over regulation during meiosis (RNF212), and tumor suppression (ZDHHC14, MIR138-2, and PHTF1)." (PMID 36535927, 2022). "We encountered samples with weak or no detectable immunoreactivity for BLCAP, although these constituted only a minor part (8%; 8 out of 101 tumor samples) of the total number of samples." (PMID 23049907, 2012). "We found that the staining intensity, and consequently the expression of BLCAP, varied widely from sample to sample, ranging from non-detectable to strong, both for normal and tumor samples." (PMID 23049907, 2012). "However, EZH2 knockdown with or without PRADX overexpression in tumor cells revealed increased levels of BLCAP and reduced nuclear levels of p-STAT3." (PMID 35574370, 2022). "Moreover, we showed that BLCAP interacted with STAT3 and reduced STAT3 phosphorylation, overexpressed PRADX activated STAT3 phosphorylation, and promoted ACSL1 expression via suppressing BLCAP expression, accelerating tumor metabolism." (PMID 35574370, 2022). "Consequently, it is conceivable that the tumor suppressive effect of BLCAP is not functional in mammary epithelial cells." (PMID 23049907, 2012). "Moreover, none of the other histopathological parameters we assessed, specifically: tumor size and age, nodal status or BRE histologic grade (according to Elston and Ellis), ER status, PR status, or Her-2/neu status showed any statistically significant correlation with BLCAP staining score." (PMID 23049907, 2012).
cancer (20 papers, 2010 to 2025). A tumor composed of atypical neoplastic, often pleomorphic cells that invade other tissues. "We have found only one gene related to anti-CTLA-4 resistance: BLCAP or Bladder Cancer Associated Protein." (PMID 37055532, 2023). "Notably, the recurrent promoter mutation in BLCAP, a suspected cancer gene, is also predicted to create an ETS binding site, while KBTBD8 plays a critical role in melanocyte differentiation." (PMID 37169747, 2023). "The bladder cancer-associated protein (BLCAP) gene encodes a protein that stimulates apoptosis." (PMID 35063012, 2022). "Recently, in a study about A>I(G) RNA editing across all available cancer cell lines, only two RNA-edited sites, Chr19:58355670 (A/G) in ZNF587B and Chr20:36147563 (T/C) in BLCAP, were associated with sensitivity to doxorubicin specifically in BC cell lines." (PMID 38672084, 2024). "Of special interest are the pre-mRNAs encoding AZIN1, BLCAP, SON and GLI1, all of which display dysregulation in various cancer types." (PMID 34882682, 2021). "Although the function of BLCAP has been examined in preliminarily studies, how BLCAP plays an anti-oncogenic role and edited BLCAP functions as a cancer driver still require further exploration." (PMID 28455960, 2017). "In addition, similar findings regarding the phenomenon that over-edited BLCAP promotes cancer progression were obtained in another study on cervical cancer." (PMID 38233935, 2024). "AZIN1 and BLCAP have been shown to promote tumorigenesis in various cancers." (PMID 37328893, 2023). "For example, AZIN1 and BLCAP promote cancer development after editing." (PMID 37328893, 2023). "BLCAP with RNA editing at this site was found to lose its ability to inhibit signal transducer and activator of transcription 3 (STAT3), providing a clue that the Y/C editing site in BLCAP is associated with the function of BLCAP and the development of cancer." (PMID 30918658, 2019). "The editing level of BLCAP differs greatly among cancer types." (PMID 28455960, 2017). "Taken together these data indicate that BLCAP may have multiple, tissue-specific functions in cancer cells, with one or more of those function(s) conferring a more aggressive behavior to cancer cells." (PMID 23049907, 2012). "To determine the proportion of cases showing up-regulation of BLCAP with neoplastic transformation, we performed additional quantitative IHC analysis of only the matched pairs of samples, consisting of normal and corresponding carcinoma, from the DCTB dataset." (PMID 23049907, 2012). "In addition to TERT, BLCAP, and KBTBD8, we also observed low levels of damage induction in UV-irradiated melanocytes at a number of other recurrent mutations in the promoters of known or suspected cancer genes (i.e., TCF3, TOP2A, NUMB, FOSB, and OTUB2)." (PMID 37169747, 2023). "Therefore, in cancers, BLCAP transcript is not only downregulated but is also less edited." (PMID 19908260, 2010). "Moreover, we report that editing of the BLCAP transcript is downregulated in cancerous tissues that could be of importance for future-improved diagnosis and prognosis in a variety of different cancer types." (PMID 19908260, 2010). "Over-expression of BLCAP in human TC-135 Ewing’s sarcoma cells, Tca8113 tongue carcinoma cells, and HeLa cervical cancer cells can inhibit cell growth and induce apoptosis, suggesting that Blcap may regulate cancer cell proliferation and survival, and play a role in cellular carcinogenesis." (PMID 29190807, 2017). "Of these, AZIN1, BLCAP, ITGA2, GLI1, NEIL1, and CDK13 after the editing promote cancer development." (PMID 37328893, 2023). "Furthermore, by resorting to several recent review articles, there were 26 RESs with cancer‐related clinical significance that were covered by our dataset, which resided in 7 genes (AZIN1, BLCAP, COG3, COPA, FLNB, GRIA2, and NEIL1)." (PMID 34319007, 2021).
cancer (continued). "It was shown that wild-type BLCAP could inhibit the phosphorylation of signal transducer and activator of transcription 3 (STAT3) by directly interacting with it, whereas over-edited BLCAP lost its ability to inhibit STAT3 activation, which in turn promoted cancer progression." (PMID 38233935, 2024).
BLCAP also shares sentences with these, for which no sentence is quoted: colorectal cancer (4 papers); ovarian carcinoma (2); tongue cancer (2); Azoospermia (1); brain tumor (1); breast (1); carcinoma in situ (1); ductal carcinomas (1); Ewing sarcoma (1); glioblastoma (1); Infertility (1); invasive carcinoma (1); invasive lobular carcinoma (1); liver cancer (1); multiple myeloma (1); oral cavity cancer (1); pancreatic cancer (1); prostate carcinoma (1); renal carcinoma (1); schizophrenia (1); triple-negative breast carcinoma (1); viral infection (1); Wilms tumor (1).